E2F4 (E2F transcription factor 4)
Diseases named in the same sentence as E2F4 in open-access papers (continued):
Sharing a sentence is not in itself a finding about the gene and the disease.
tumor (continued). "Although E2F4 has been reported to enhance tumor cell proliferation, there is no literature addressing whether the effects of E2F4 in cancer growth are associated with ferroptosis." (PMID 40600459, 2025). "Conversely, tumor development is delayed by the absence of E2F4." (PMID 19749980, 2009). "Recent evidences show E2F4 may play an oncogenic rather than a tumor suppressor role in cells." (PMID 25650659, 2015). "The results showed that the expression levels of E2F2, E2F3, E2F6, and E2F8 are significantly correlated with the tumor stage of PAAD patients, while the expression levels of E2F1, E2F4, E2F5 and E2F7 are not correlated with the tumor stage of PAAD patients." (PMID 33604289, 2020). "In addition, NOP14 induced expression of transcription factor E2F4 independent of miR17-5p/P130 signaling, which simultaneously activated a set of targeted genes, such as CCNE1, PIM1, AKT1 etc., to promote tumor proliferation." (PMID 37506248, 2023). "However, the analysis of the data in this study found that the transcription levels of E2F4 in PAAD were not different from that in normal tissues and had nothing to do with the tumor stage of PAAD patients." (PMID 33604289, 2020).
cancer (83 papers, 2008 to 2025). A tumor composed of atypical neoplastic, often pleomorphic cells that invade other tissues. "E2F4 is a key regulator of cell cycle that is widely associated with tumorigenesis and cancer severity." (PMID 35101047, 2022). "E2F4 expression was found to be significantly associated with immune cell infiltration among several cancers, especially in HCC." (PMID 33613768, 2021). "E2F4 is an essential cell cycle regulator that has been broadly implicated in tumorigenesis and cancer severity." (PMID 28464832, 2017). "E2F4 plays an important role in the suppression of proliferation-associated genes, its gene mutation and increased expression are associated with human cancers." (PMID 25650659, 2015). "E2F transcription factor 4 (E2F4), a member of the E2F family of transcription factors, plays an important role in inhibiting proliferation-associated genes, and its gene mutation and increased expression are related to different cancers." (PMID 33968141, 2021). "Abnormal expression of E2F4 and its mutations are reported in several cancers including NSCLC." (PMID 31681566, 2019). "Furthermore, transgenic mice overexpressing E2F4 develop tumors, and mutated E2F4 has been reported in several types of cancers, including cancers of the gastrointestinal tract and prostate, suggesting a broad tumorigenic role for E2F4." (PMID 25440089, 2014). "The members of the family E2F1, 2, 3 and E2F4 have been reported to be associated with cancer." (PMID 22041030, 2011). "We identified E2F4 and FOXM1 as transcription factors strongly associated with adaptation to aneuploidy in vitro and in cancers and validated this finding." (PMID 39930267, 2025). "Understanding E2F4's function and regulation is pivotal for deciphering the molecular intricacies of tumorigenesis and devising targeted cancer treatments." (PMID 39309429, 2024). "In HCC, E2F4 was significantly increased and promoted cancer progression via transcriptionally upregulating CDCA3 expression." (PMID 39309426, 2024). "We systematically interrogated the Cancer Therapeutics Response Portal datasets, and found that E2F4 expression correlated with resistance to ferroptosis inducers ((RSL3, ML210 and ML162, which inhibit GPX4 activity)." (PMID 38575587, 2024). "This included ERα, the transcriptional repressor protein E2F-4, the microtubule protein αTubulin and proteins involved in cancer cell metabolism (GLUT1, LDHA and PDK1-pSer241) and stress responses (eIF2A-pSer51)." (PMID 37596623, 2023). "In cancer, E2F4 appears to act primarily as an oncogene, which is more consistent with its role in promoting proliferation rather than its classic inhibitory effect on the cell cycle." (PMID 36567912, 2022). "We similarly found a significant enrichment in E2F‐4 and E2F‐3 transcription factors with the enrichment analysis of differentially expressed genes in carcinoma." (PMID 35488454, 2022). "This is also consistent with the motif enrichment result that enriched TFs in the PRC2−-CGI class were strongly overlapped between different cancer types, and were associated with cell-cycle TFs, such as SP1, JUND, NFY, E2F4, and E2F1." (PMID 33931649, 2021). "In this study, we observed that E2F4 expression was dysregulated in pan-cancer, and especially in HCC." (PMID 33613768, 2021). "The silencing of E2F4 diminished proliferation of human intestinal epithelial cells and CRC cells, which supports the regulatory role of E2F4 in cell progression in cancers." (PMID 32314545, 2020). "E2F4 has also been found with the MYC transcriptional activator at regulatory regions of genes involved in cancer development." (PMID 31270324, 2019).
cancer (continued). "Future work will be needed to identify the different protein complexes that E2F4 contributes to and the plethora of cellular functions that are controlled by this major E2F family member, including in stem cells and cancer cells." (PMID 31270324, 2019). "E2F4 is a key regulator of cell transformation, proliferation, and cell cycle progression, and a recent study showed that patients exhibiting high expression of E2F4 target genes exhibited more severe cancer and shorter survival." (PMID 30967995, 2019). "This study provides important findings for USP24-mediated protein turnover including p300, Bax, E2F4 and securing to regulate apoptosis and proliferation of cancer cells, respectively, which is crucial for cancer tumorigenesis." (PMID 27991932, 2017). "E2F4 is a key regulator of the cell cycle, and patients exhibiting high expression of E2F4 target genes exhibit more severe cancer and shorter survival." (PMID 28464832, 2017). "Consistently, E2F4 drives proliferation in stem and progenitor cells and in cancer cells, which are rapidly cycling and in which the RB family proteins are inactive or mutated." (PMID 27753528, 2016). "In cancers, E2F4 appears to act primarily as an oncogene, which is more consistent with its non-canonical role in pro-proliferative cells than with its canonical, repressive role in the cell cycle." (PMID 27753528, 2016). "Knockdown of E2F4 in these contexts prevents G2 arrest and sensitizes cancer cells to irradiation-induced apoptosis." (PMID 27753528, 2016). "We then computationally calculated the regulatory activity score (RAS) of E2F4 in cancer tissues, and examined how E2F4 RAS correlates with patient survival." (PMID 25440089, 2014). "Analysis of E2F4 levels in these subtypes showed a significant variation among them, with lower levels of E2F4 activity seen in a greater fraction of cancer samples classified into intrinsic subtypes with better prognosis." (PMID 25440089, 2014). "c-Myc and E2F4 play important roles in cancer cells, and a large portion of our microarray data collection is related to cancer." (PMID 21698123, 2011). "The gene expression changes in model cells aligned with gene expression changes observed in aneuploid cancers and uncovered the transcriptional factors E2F4 and FOXM1 to critically contribute to adaptation to chromosome gains, which we experimentally validated." (PMID 39930267, 2025). "Such insights provide a framework for future studies aimed at disentangling the relative contributions of RB, p107, p130, and E2F4 in normal physiology and in cancer, where this regulatory circuitry may be disrupted." (PMID 41155196, 2025). "Additionally, the expression of MCM2, PNCA, and E2F4 genes was reduced in COLO-205 cancer cell lines." (PMID 40872562, 2025). "Our data also indicated increased expressions of c-Myc, E2F4 and E2F5 genes, encoding transcription factors, which might be an attempt by cancer cells to stimulate their growth." (PMID 38674023, 2024). "Furthermore, the interplay between NRF1 and E2F4 transcription factors was previously shown to contribute to cancer development and progression." (PMID 37627157, 2023). "Contributions of the ΔNp73α-E2F4/p130 complex in cancer cells." (PMID 36883841, 2023). "Furthermore, the detection of a ΔNp73α-E2F4/p130 complex in extracts of the HPV-negative HNC-136 cancer cell line confirms that the ΔNp73α-E2F4 interaction is independent of the viral oncoproteins." (PMID 36883841, 2023). "Because several studies have highlighted the importance of ΔNp73α in different types of cancer, we evaluated whether the ΔNp73α-E2F4 interaction occurs in cancer-derived cell lines." (PMID 36883841, 2023).
cancer (continued). "We show that the ΔNp73α-E2F4/p130 complex inhibits the expression of specific genes, including genes encoding for negative regulators of proliferation, both in 38HK and in HPV-negative cancer-derived cell lines." (PMID 36883841, 2023). "Genes containing AS events associated with overall survival are known components of cancer-related pathways, including regulation of transcription (E2F4, ZNF730, GPBP1, POLR2J, SP2, and CIART), cell cycle (E2F4 and GTSE1), or cell-cell adhesion (CEACAM1, MMP14, EPS8L2, AP3D1, AFDN, and PAK4)." (PMID 35044822, 2022). "Interestingly, recent studies showed that the higher expression of COX4NB, E2F4, and NAE1 was associated with poor prognosis in various cancers, suggesting its cancer-promoting role." (PMID 35155261, 2022). "Finally, E2F4, FOXC1 and KDM2B play oncogenic roles in other types of cancer as well, supporting their identified pathogenic potential in HL." (PMID 34807923, 2021). "The results showed that the transcription of E2F4 was increased in most cancers." (PMID 33613768, 2021). "In addition, many high centrality differentially regulated genes in cancer were regulated by the E2F family genes, of which E2F4 alone regulates about 344 genes." (PMID 34728699, 2021). "UALCAN was used to analyze the expression of E2F4 mRNA from the pan-cancer data." (PMID 33613768, 2021). "E2F4 was also reported to play important roles in the cell progression in various cancers." (PMID 34252883, 2021). "The next one, E2F4, is a transcriptional repressor involved in many different functions in the cell, such as cell cycle regulation and regenerative processes in stem cells and in cancer." (PMID 34941772, 2021). "Similarly, markers of E2F-dependent transcription are mostly represented overall cancers types, as well as E2F4 and TFDP1, which regulate genes involved in key processes of malignant transformation, such as cell cycle regulation and DNA replication." (PMID 32015379, 2020). "Several cancer types exhibit E2F4 amplification or overexpression." (PMID 31270324, 2019). "E2F4 has a crucial role in cell cycle progression and is related to several cancers." (PMID 30020984, 2018). "In conclusion, the USP24 level was decreased during the early stage of cancer and the mitotic stage of the cell cycle to regulate its substrates p300, Bax, E2F4 and securin, resulting in decreased cell apoptosis and increased cell cycle progression and, thus, cancer formation." (PMID 27991932, 2017). "Finally, the role of E2F4 in undifferentiated embryonic stem cells (ESCs) and cancer cells remains to be explored." (PMID 27753528, 2016). "As ESCs and cancer cells are similar in cell cycle structure, research on E2F4 in ESCs might inform research in cancer biology, and vice versa." (PMID 27753528, 2016). "For example, human cytochrome c1, whose gene is regulated by E2F, participates in an electron transport chain and the mitochondria pathway of apoptosis whereas a similar set of electron transport-related genes (COX8, CYB5-M, CYP51A1, FDXR and SUCLG1) were found to be E2F4-bound in cancer cell lines." (PMID 22076139, 2011). "Higher PCCs were observed for most transcription factors in both cancer conditions, with the exception of E2F4 in prognosis and treatment response (P values obtained using the empirical distribution of random PCCs (empirical P values) were of 0.16 and 0.11, respectively)." (PMID 19229342, 2009). "Cancers displaying unfavorable risk with high ALT (BRCA, SARC, and LUAD) may be regulated by the transcriptional factors E2F4, TFDP1, E2F1, E2F7, and SIN3A (FDR = 0.001) in the DNA repair pathway, including genes repairing DNA damage such as CENPI, CLSPN, TOPBP1, and MCM4." (PMID 32784588, 2020).
cancer (continued). "Similarly, abundant studies demonstrated that E2F4, STAT1, MYC, ERG, and NFYB may play an important role in the pathogenesis and progression of various cancers, including OSCC, and the underlying mechanism may be related to dysregulated lncRNA." (PMID 32923393, 2020). "The data indicated that there was a high relevance between the USP24 level and the substrates identified in this study, suggesting that USP24 might regulate p300, Bax, E2F4 and securin levels to regulate apoptosis and cell cycle progression, resulting in cancer formation." (PMID 27991932, 2017). "However, recent observations challenge this paradigm and indicate that E2F4 has a multitude of functions in cells besides this cell cycle regulatory role, including in embryonic and adult stem cells, during regenerative processes, and in cancer." (PMID 27753528, 2016). "Additionally, ESCs resemble cancer cells in their DNA damage response, and thus E2F4 may mediate G2/M arrest or repress DNA damage repair genes in both cell types through similar mechanisms." (PMID 27753528, 2016). "Strikingly, the consensus targets of transcription factors E2F4 and FOXM1 were strongly enriched in our in vitro evolution model, as well as in aneuploid cancers." (PMID 39930267, 2025). "This analysis revealed a significant enrichment of E2F4 and FOXM1 targets in evolved cancer cell lines and in aneuploid tumors." (PMID 39930267, 2025). "E2F transcription factor 4 (E2F4) is a member of the E2F family and plays a pro- or anti-tumorigenic role in a variety of cancers." (PMID 37349788, 2023). "In the Myc datasets (GSE22139, GSE11791), multiple top-ranked TFs, such as MAX, SP1, NRF1, and E2F4, are known to interact with MYC in regulating the expression of common target genes in cancer cells." (PMID 38032891, 2023). "E2F1 and E2F4 chromatin immunoprecipitation sequencing (ChIP-seq) data analyses from cancer cells (E2F1 ChIP-seq, E2F4 ChIP-seq, RBL2/p13055) further indicated the binding of E2F1 and E2F4 in the proximity of WNT4 and WNT8A." (PMID 37725511, 2023). "The downexpression of these miRNAs significantly reduced cancer cell proliferation and apoptosis by targeting FOXO-3, CLSPN, ACVR1B, E2F4 and PPP2CA and regulated cell cycle progression by targeting CDKN2A and FOXO-3." (PMID 34743742, 2021). "Previous studies have reported that the aberrant expression of Timeless in cancer is activated byERK signaling pathways, or by transcription factors such as E2F1 and E2F4." (PMID 33971927, 2021). "Because the transactivation domain of E2F4 is normally inhibited upon RB family binding, we speculate that the pro-proliferative role of E2F4 may be restricted to cell types where the RB family proteins are inactive, as in rapidly cycling progenitor cells and cancer cells." (PMID 31270324, 2019). "KIF2C and KIF20A were reported, in a study based on ChIP-chip assays, as the target of E2F family including E2F1, E2F4, and E2F6 in normal and cancer cells of breast tissue." (PMID 30813560, 2019). "E2F4 is one of the downstream genes of the TGF-beta signaling pathway and leads to the apoptosis of cancer cells." (PMID 30279327, 2018).